IL25 (interleukin 25)
Diseases named in the same sentence as IL25 in open-access papers (continued):
Sharing a sentence is not in itself a finding about the gene and the disease.
infection (continued). "Complete resistance to infection in rIL-25-treated mice was associated with an early enhanced expression of terminal α-L-Fucosyl terminals (Fuc) residues in extracellular mucus and goblet cell vesicles, which is induced by IL-25 administration prior to infection." (PMID 27658962, 2016). "Interestingly, metacercariae challenge of resistant rIL-25-treated mice induced a peak of IL-12p35, though the presence of IL-25 prevented the development of a Th1 phenotype as it occurs in primary infections in naïve mice." (PMID 27658962, 2016). "In contrast, tuft cell hyperplasia induced by inoculation with exogenous IL-25 or due to epithelial restoration after cure of a primary infection enhanced tuft cell expansion and endogenous IL-25 production facilitating the development of protective Th2 responses with elevated levels of IL-13." (PMID 27658962, 2016). "This was confirmed by treatment of naïve mice with exogenous IL-25 and subsequent infection." (PMID 27658962, 2016). "This boost of IL-25 induced by the cure of the primary infection may determine resistance against secondary infections." (PMID 27658962, 2016). "Finally, exogenous IL-25 significantly decreased the abundance of SFB and the expression of IL-17-associated genes in the ileum similar to infection with N. brasiliensis." (PMID 26377648, 2015). "Next, we investigated whether there were changes in the cytokine milieu at the site of infection using the thoracic cavity lavage and assessed the levels of several cytokines: IL-4, IL-5, IL-13, IL-25, IL-33, and IFNγ." (PMID 24663956, 2014). "Thus, IL-25 KO mice treated with IL-25-elicited MMPtype2 cells had reduced worm numbers at day 20 post infection compared to the untreated controls." (PMID 23053395, 2012). "Dysregulation of the tuft/IL-25 axis, driven by infections, microbial metabolite fluctuations, or environmental factors (including regional variations in helminth exposure linked to the hygiene hypothesis), is increasingly recognized as a significant contributor to IBD pathogenesis." (PMID 41041315, 2025). "The primacy of the IL‐25 response circuit to Nb immunity has largely rendered questions around IL‐33 responses to the parasite secondary, but interesting research has emerged drawing into focus some points of contention in IL‐33 research, using the Nb infection model." (PMID 40944312, 2025). "However, the role of IL-25 in intestinal tuft cells training to fight with infection is intriguing." (PMID 39261649, 2024). "In summary, our findings demonstrate that during the early phase of PSV-S infection, mucosal type 2 immunity expands to involve tuft cells and cholinergic nerves, as evidenced by the increased presence of tuft cells, cholinergic nerves, IL-25, and type 2 cytokines." (PMID 37937994, 2023). "Recently, however, two studies have reported RV-C15 – a prevalent strain in humans that may cause severe symptoms – infection of C57BL/6J mice induced the upregulation of remodeling-associated genes MUC5AC and MUC5B, elevated IL-25, IL-33, and TSLP levels, and increased numbers of lung ILC2s." (PMID 37773065, 2023). "Since the epithelial cell-derived cytokine IL-25 and IL-33 were known to mediate the progression of cryptococcal diseases caused by C. neoformans infection by amplifying Th2-type immune response, we further analyzed how IL-25 acted together with IL-33 to regulate CD4+ T helper cell during infection." (PMID 37337050, 2023). "Previous studies indicated that pulmonary IL-25 was upregulated in response to C. neoformans infection later than IL-3320, indicating that these cytokines may preferentially function in promoting cryptococcal disease pathogenesis at different infection stages." (PMID 37337050, 2023). "Furthermore, IL-25 expression was identificated by iFA after infection with rHEP-IL25 in NA cells." (PMID 35999776, 2022).
infection (continued). "The results obtained showed that resident microbiota play a major role in the production of IL-25 and the appearance of members of the phylum Verrucomicrobia as a consequence of the curation of the primary infection could be related to the partial resistance to secondary infection." (PMID 36176223, 2022). "Hence, the presence of the ST2- IL-9+ ILC2 population in the small intestine described here might be explained by this regulatory loop, where IL-33 and IL-25 are induced upon infection, promoting iILC2s that lack ST2 and express effector cytokines in vivo." (PMID 35711429, 2022). "Given the previous evidence that IL-25 is extensively downregulated in the infection of protozoans and the supplement of IL-25 is beneficial for treating protozoan infections, more studies are needed to better elucidate the mechanism of IL-25 in protozoan infections." (PMID 36119076, 2022). "However, IL-25 could have a role in the differentiation of the Th2 memory subset, facilitating Th2 responses to challenge infections." (PMID 33276813, 2020). "Together, these data indicate that the IL-25-responsive iILC2 subset aids in mobilizing the immune response for rapid pathogen clearance and acts distinctly from tissue-resident IL-33-responsive subsets particularly in settings where IL-25 dominates the early alarmin response to infection." (PMID 32793230, 2020). "A number of laboratories have reported that IL-25 upregulation is induced by infection with intestinal helminths, such as Nippostrongylus brasiliensis, Trichinella spiralis, Trichuris murisor and Heligmosomoides polygyrus, leading to activation of type-2 responses and resistance to infection." (PMID 33276813, 2020). "IL-25 has been demonstrated to be induced on day 1 following T. spiralis infection, which may be followed by promoting the induction of IL-25 responsive ILC2s in the early stage of infection." (PMID 28898280, 2017). "In the absence of IL-25, the early production of both subunits of IL-12 (IL-12p35 and IL-12p40) may be essential for the determination of the susceptibility to infection." (PMID 27658962, 2016). "Strikingly, expression of regulatory factors (IL-10, IL-25, Foxp3), which arise following H. diminuta infection, were either enhanced or sustained in IL-22-/- mice, uncovering a novel role for IL-22 as a brake for these regulatory events following infection with this parasitic helminth." (PMID 27055194, 2016). "This confirms that E. caproni infection in ICR mice does not activate IL-25 expression but, in contrast, induces IL-12 production which may explain the susceptibility to E. caproni primary infection." (PMID 27658962, 2016). "Notably, mice deficient in IL-25 (IL-17BR−/−) or IL-33 (T1/ST2) receptors mount poor type 2 responses and are more susceptible to infection with Nippostrongylus brasiliensis, while immunity can be restored to these animals by transfer of ILCs acting in an IL-13-dependent manner [13••]." (PMID 22795966, 2012). "Alarmin cytokines, such as IL-25, IL-33, and TSLP, are secreted by various immune and epithelial cells in response to tissue damage, infection, or inflammation." (PMID 38396704, 2024). "Transcriptome profiles of IL-25- and IL-33-treated pulmonary effector CD4+ T cells were analyzed by comparing upregulated genes in Il17rb−/− mice and wild-type mice during infection." (PMID 37337050, 2023). "Interestingly, both primary and challenge infection depleted the presence of members of Verrucomicrobia that only appeared as a consequence of the curation of the primary infection, concomitantly with the upregulation of IL-25 and the subsequent resistance to infection." (PMID 36176223, 2022). "IL-33, in the presence of IL-25, potentiates ILC2 populations to produce IL-13 to promote intestinal remodeling to facilitate infection resistance with helminths and parasites." (PMID 33431701, 2021).
infection (continued). "IL-25, an alarmin that strongly activates ILC2, was rapidly secreted in response to immunization or infection and its administration to mice significantly increased IgM production and B1 cell differentiation to ASC." (PMID 34449811, 2021). "Upon secondary infection with E. caproni (i.e., post-drug clearance of the primary infection) both ETC hyperplasia as well as an increase in tissue IL-25 levels were observed alongside worm clearance." (PMID 34578195, 2021). "In contrast, IL-25 and TSLP levels fluctuated over the course of infection, peaking around the tenth week of infection, with TSLP at much lower levels than IL-25." (PMID 33482904, 2021). "Compared to sham treatment, RV-C15 infection significantly increased mRNA expression of IFN-γ, CXCL10, CXCL1, CXCL2, TNF-α, IL-12, IL-25, IL-13 and IL-5." (PMID 33968043, 2021). "Initial RSV response is driven by innate cytokines, such as IL-25, IL-33, and thymic stromal lymphopoietin (TSLP) that are released from the airway epithelial cells following infection." (PMID 32375305, 2020). "ConA and LsAg induced IL-25 release from thoracic cavity cells of ST2-ko and WT animals was comparable and peaked at 35 dpi and declined with the duration of infection." (PMID 24663956, 2014). "Exogenous IL‐25 administration has, however, been shown to render normally susceptible AKR mice resistant to HD Tm infection, but not SCID mice lacking T and B cells." (PMID 40944312, 2025). "Interestingly, the intestinal adiponectin expression was strongly associated with the expression of epithelial cell-derived cytokines IL-25, IL-33, and TSLP following infection." (PMID 37635188, 2023). "Previous studies have indicated that infection with C. neoformans stimulated lung epithelial cells to secrete IL-25 and IL-33 but not TSLP19–22." (PMID 37337050, 2023). "On the 14 days post-infection, the effector CD4+ T cells (CD3+CD4+CD44hiCD62Llo) were sorted from lungs and ex vivo stimulated with recombinant IL-25 or IL-33 or the combination of IL-25 and IL-33." (PMID 37337050, 2023). "The release and function of TSLP by dermal TRMs during L. major infection appears to be non-redundant, as neither IL-33 nor IL-25 transcripts were detected in the dermal TRM cluster, and mice deficient in these cytokines did not alter their infection outcome." (PMID 38030609, 2023). "However, IL-25 treatment inhibits the expression of IFN-γ, which is beneficial for the infection of HSV-1." (PMID 36119076, 2022). "In fact, no change in IL-25 expression was observed during the entire experiment in that group of mice that were only subjected to a primary infection." (PMID 36176223, 2022). "In E. caproni-infected mice, ETC hyperplasia was observed during a chronic, Th1-inducing primary infection, with no concurrent increase in the intestinal levels of IL-25." (PMID 34578195, 2021). "As intra-nasal administration of IL-25 or IL-33 can also recruit ILC2s into BALF without infection or allergen exposure, these cytokines potently mediate migration of ILC2s into BALF." (PMID 33403383, 2021). "Similar to taste cells, ETC activation following infection with parasitic helminths is dependent on TRPM5: the cation channel, which aids in the depolarization of the cell (Ca2+ ion activated and allowing influx of Na+ ions) and exocytosis of IL-25." (PMID 34578195, 2021). "Five of these mice were treated with mα-IL-25 before a challenge E. caproni infection at 2 wppt; the remaining five mice were given a secondary infection at the same time without mα-IL-25 treatment." (PMID 33276813, 2020). "Our study shows that the mice were also unable to produce IL-25 in a secondary challenge infection, but that even in the absence of IL-25 secondary E. caproni infection at 2 wppt induced a Th2 response." (PMID 33276813, 2020). "In contrast to primary infection, secondary infection elicits a type-2 response, even in the absence of IL-25 expression." (PMID 33276813, 2020).
infection (continued). "The results obtained show that blockade of the IL-25 reverted the partial resistance to infection and that the number of worms recovered was significantly higher in the animals treated with mα-IL-25 than in the non-treated mice at necropsy." (PMID 33276813, 2020). "The worm recovery in secondary infections in the absence of IL-25 (46–59%; mean ± SD: 54.2 ± 11.1%) was similar to that of observed in the animals of the same age primarily infected [49–61%; 58.6 ± 13.6)." (PMID 33276813, 2020). "The profile of cytokine mRNA expression showed that secondary infection at 10 wppt induced the development of a Th2 phenotype despite the lack of IL-25 at the time of infection." (PMID 33276813, 2020). "The results show that primary infection of mice with E. caproni did not elicit IL-25 upregulation, but pharmacological cure of the primary infection induced a marked overexpression of IL-25." (PMID 33276813, 2020). "In contrast to the situation that occurs in primary infections, IL-25 does not appear to be required for the development of Th2 responses in secondary E. caproni infections." (PMID 33276813, 2020). "In contrast to primary infection, secondary infection elicits a type-2 immune response even in the absence of IL-25 expression." (PMID 33276813, 2020). "IL-25 levels were less than the limit of detection, as determined by using ELISA, across the first 96 hours after infection (data not shown)." (PMID 27156176, 2016). "This implies that TSLP is not likely to beimportant in conditioning the dermal immune response in our multiple infection model butdoes not rule out other cytokines such as IL-25 or IL-33 recently described to beimportant for Th2 induction." (PMID 21445234, 2011). "WT mice displayed significant increases in Retnla, Il4, Il5, Il13, and Ccl11 (Eotaxin) mRNA expression following infection with N. brasiliensis, while Il25 and the mucin genes Muc5ac and Gob5 were not altered." (PMID 19381262, 2009). "Mechanical injury, infection, inflammatory cytokines and proteases such as trypsin and papain stimulate the release of various cytokines of epithelial origin, such as thymic stromal lymphopoietin (TSLP), interleukin-25 (IL-25), interleukin-33 (IL-33) and periostin." (PMID 40981017, 2025). "Mast cells release IL-25 and IL-33 in response to H. polygyrus-induced release of ATP from epithelial cells and mast cell-derived IL-33 induces ILC2 production of IL-13: both events have the potential to drive ETC hyperplasia as a response to infection with helminth parasites." (PMID 34578195, 2021). "As ETCs are suggested to be the dominant epithelial source of IL-25, it is likely that IL-25 release upon T. spiralis infection is ETC derived; however, tuft cell specificity in the activation of the bitter taste receptor in this model of infection requires rigorous testing." (PMID 34578195, 2021). "Animals treated with mα-IL-25 showed a similar cytokine profile to non-treated mice, and in both groups, a type-2 response was generated with elevated gene expression of IL-4 and IL-13 after the challenge infection." (PMID 33276813, 2020). "We previously reported that IL-25 was important in promoting efficient protective immunity against T. spiralis infection; however, the cellular targets of IL-25 to elicit type-2 immunity during infection have not yet been addressed." (PMID 28898280, 2017). "However, the expansion of the tuft cell lineage was not accompanied by an increase in IL-25 expression in E. caproni primary infection." (PMID 27658962, 2016). "However, the lack of IL-25 overexpression was striking, especially considering that infection induced a marked tuft cell hyperplasia." (PMID 27658962, 2016). "However, the role of IL-25 in resistance to infection is not well defined." (PMID 32616023, 2020). "In nonpolarized macrophages, this enhancement of infection by JEV was statistically significant for IL-33 alone, for IL-33 combined with TSLP, and for IL-33 combined with TSLP and IL-25." (PMID 30282716, 2018).
infection (continued). "In sharp contrast, the i-Raptor−/− mice did not respond to Tm infection as demonstrated by the lack of DCLK1 expression and IL-25 in epithelium and IL-13 in lamina propria." (PMID 28717211, 2017). "Within the first 5 days of infection, the absolute numbers of ILC2 did not significantly change in the dermis, which is in line with the unaltered expression of cytokines activating (IL-18, IL-25, IL-33, TSLP) or inhibiting ILC2 (IL-27, IFN-γ)." (PMID 35894051, 2022).